MALAT1 (metastasis associated lung adenocarcinoma transcript 1)
Diseases named in the same sentence as MALAT1 in open-access papers (continued):
Sharing a sentence is not in itself a finding about the gene and the disease.
cancer (continued). "Relative plasma expression of SOX2, PIWI proteins, and MALAT1 by qRT-PCR in cancer and control groups." (PMID 40674376, 2025). "The long non-coding RNA MALAT1 is overexpressed in multiple cancers, but its precise mechanistic role and downstream regulatory network in HCC remain incompletely understood." (PMID 40958861, 2025). "MALAT1, an oncogenic lncRNA, promotes cancer progression through various mechanisms, such as miRNA sequestration, autophagy stimulation, and the induction of epithelial-mesenchymal transition." (PMID 40860202, 2025). "Although test-tube assays are informative, cell-based assays are needed to determine if small molecules can decrease MALAT1 levels, which is the desired outcome to treat most MALAT1-upregulated human diseases, particularly cancer." (PMID 41226238, 2025). "Investigations concerning UCA1 and HOTAIR, analogous to those on MALAT1, have primarily concentrated on the downregulation of these lncRNAs and the subsequent diminution in cancer progression." (PMID 40699668, 2025). "And ASOs-based silencing of MALAT1 led to reduced cancer metastasis and reversed therapeutic resistance in various types of human cancers." (PMID 40236651, 2025). "MALAT1 can affect cancer cell plasticity through its molecular actions by facilitating EMT, a crucial phenotypic change associated with increased cell proliferation and migration." (PMID 41013839, 2025). "It was found to be upregulated with oncogenic function in most cancer types, including lung, colorectal, and thyroid cancers, while in other types of cancer, such as glioma and endometrial carcinoma, MALAT-1 was found to be a tumor suppressor." (PMID 39798064, 2025). "As miR-155 can induce PD-1/PD-L1 expression directly through binding to the 3′-UTR region, or indirectly through upregulating the long non-coding RNAs (MALAT-1) in cancer patients." (PMID 40108523, 2025). "Meanwhile, MALAT1, which differentially expressed in multiple cancer types, has garnered attention as a potential biomarker in recent studies." (PMID 40597438, 2025). "The lncRNA MALAT1 has been reported to influence the transcriptional regulation of drug resistance genes, including P-gp, in cancer cells." (PMID 40352931, 2025). "Current studies show that MALAT1 is a potential target not only for cancer therapy, but also for overcoming cancer resistance." (PMID 40258843, 2025). "Single-gene gene-set enrichment analysis (sgGSEA) further highlighted the strong association between MALAT1 and HBV infection, as well as with cancer-related signaling pathways." (PMID 40860202, 2025). "Beyond its roles in RNA splicing and transcriptional regulation, MALAT1 modulates various cancer-related biological processes, including proliferation, migration, and invasion." (PMID 40958861, 2025). "Although one of the first identified lncRNA much about MALAT1 in its roles in normal tissue homeostasis and furthermore its eclectic roles in regulating cancer remain to be fully understood." (PMID 40521240, 2025). "MALAT1 is a highly expressed long non-coding RNA (lncRNA) in cancer tissue, primarily functioning as an oncogene." (PMID 40223929, 2025). "Prior research confirms the presence of SOX2, PIWI proteins, and MALAT1 in plasma of cancer patients, supporting their relevance as non-invasive biomarkers." (PMID 40674376, 2025). "The MALAT1 gene interacts with transcription factors and proteins, either promoting or suppressing the transcription of essential genes involved in cancer progression." (PMID 41013839, 2025). "MALAT1 affects various miRNAs, acting as endogenous RNA sponges, consequently increasing the gene expression of several essential genes involved in cancer progression and metastasis." (PMID 40863726, 2025). "This novel insight not only expands our understanding of the molecular underpinnings of HSCC but also positions MAP2K1 as a potential therapeutic target in MALAT1-driven cancers." (PMID 39319867, 2025).
cancer (continued). "By influencing the phosphorylation status and localization of these factors, MALAT1 can affect the splicing patterns of numerous pre-mRNAs, particularly those involved in cell cycle regulation and cancer progression." (PMID 40282307, 2025). "Many studies identify elevated expression of MALAT1 in malignant tumor tissues and cell lines, and our study is consistent with these findings." (PMID 39319867, 2025). "The MALAT1 RNA, which is localized in the nucleus, is implied to be involved in stress responses and diseases including cancers." (PMID 40966253, 2025). "ASOs designed to target MALAT1 have entered preclinical and clinical development for various cancers." (PMID 41221298, 2025). "Researchers are developing inhibitors or agonists targeting specific lncRNAs (e.g., HOTAIR, MALAT1) and circRNAs (e.g., circRNA CDR1as) to restore or suppress their functions, inhibiting cancer cell proliferation and metastasis." (PMID 40621472, 2025). "The discovery of positive feedback loops involving CricNOTCH1, lncRNA MALAT1, miR-34c, Myc, and xCT further enhances our understanding of proteomic complexity, particularly in the context of cancer cell survival and therapy resistance." (PMID 39846637, 2025). "The regulatory circuits involving CricNOTCH1, lncRNA MALAT1, miR-34c, Myc, and xCT elucidate how cancer cells evade cell death and resist therapy." (PMID 39846637, 2025). "The differential expression of SOX2, PIWI proteins, and MALAT1 between cancer patients and healthy controls supports their potential utility as plasma-based biomarkers for distinguishing cancer cases from non-cancer cases." (PMID 40674376, 2025). "Pan-cancer research on MALAT1 expression levels was conducted through The Cancer Genome Atlas (TCGA) database analysis." (PMID 40597438, 2025). "Although direct evidence for some of these pathways in OSCC is still emerging, these convergent mechanisms, validated across different cancers, collectively suggest that MALAT1 is a potential regulator of immunosuppressive signaling in OSCC." (PMID 41221298, 2025). "In this context, the lncRNA MALAT1 is involved in different cancer types and acts as a transcriptional regulator of oncogenes and tumor suppressors." (PMID 38791553, 2024). "The salient features of MALAT-1 include inducing EMT by activating many critical pathways in cancers, such as β-catenin, PI3K, Wnt, TGF-β, and Ezh2-Notch1." (PMID 38201661, 2024). "This approach is bolstered by the existing literature demonstrating the efficacy of MALAT1 ASOs in significantly reducing MALAT1 levels, which are known to contribute to cancer progression." (PMID 38791954, 2024). "NEAT1 and MALAT1 non-coding lncRNAs and their protein-binding partners are frequently overexpressed to similar level in different cancer types." (PMID 39322638, 2024). "MALAT1 is overexpressed and used as a prognostic biomarker in various cancer types including lung, breast, liver, pancreas, renal, colon, bladder, uterus, and cervix cancers." (PMID 38919532, 2024). "These collective findings underscore the versatile role of MALAT1 in orchestrating gene expression across various cancer types, each characterized by distinct molecular mechanisms." (PMID 39323624, 2024). "To investigate if the crosstalk between MALAT1 and molecular components of the m6A function orchestrates gene expression in cancer cells, we evaluated the functional relationship between MALAT1 and WTAP mRNA." (PMID 38862471, 2024). "As an illustration, by studying the lncRNA-MALAT1’s inhibitory effect on metabolites and assessing the outcomes by measuring the spread or proliferation of cancer cells, the study of MALAT1 is important in inhibiting the proliferation of tumor cells." (PMID 39346921, 2024).
cancer (continued). "Upregulated MALAT1 has been observed in various cancers, including CRC, and is associated with cancer metastasis, invasion, and poor prognosis." (PMID 38696425, 2024). "As outlined in the manuscript, several lncRNAs, such as HOTAIR, MEG3, and MALAT1, have shown strong correlations with cancer progression, metastasis, and resistance to therapies." (PMID 39512820, 2024). "MALAT-1 was discovered to be significantly expressed in cancer tissues from various organs, notably EOCs, which is consistent with earlier studies." (PMID 38511067, 2024). "For example, ASOs targeting MALAT1 accompanied by nanostructure system, were used to inhibit cancer metastasis." (PMID 38184597, 2024). "Upregulation of MALAT1 has also been observed in other types of cancer, such as bladder epithelial cancer, with high malignant potential." (PMID 38674413, 2024). "Ongoing research continues to uncover the intricate details of how MALAT-1 contributes to cancer biology, and potential therapeutic strategies targeting MALAT-1 are being explored." (PMID 38511067, 2024). "MALAT-1 contributes to medication resistance and cancer aggressiveness by functioning as a miR-200a sponge and encouraging ZEB1 expression." (PMID 38511067, 2024). "It has been shown that the MALAT1 interacts with this pathway, facilitating the spread of cancer and increasing apoptotic resistance." (PMID 39325172, 2024). "Our findings delineate the molecular mechanism of MALAT1 that fine-tunes the expression of specific cancer modulators, such as NR4A1, by regulating the chromatin accessibility of an NR4A1-downstream RE." (PMID 38791553, 2024). "Elevated NEAT1 and MALAT1 levels correlate with A3B activity modulation, indicating their potential as biomarkers for monitoring A3B enzymatic activity in cancer." (PMID 39322638, 2024). "Most of the ASOs target the unstructured regions of MALAT1, leading to a 2–50-fold decrease in their level by recruiting RNase-H-mediated degradation and dysregulating its function in various cancer types." (PMID 38338910, 2024). "In the functional enrichment results, MALAT1 was found to be enriched in a large number of cancer-related pathways and plays an important role in tumourigenesis." (PMID 38360815, 2024). "Many cellular processes in cancer stem cells (CSCs) that are known to initiate tumor formation can be regulated by lncRNAs such as MALAT1, ROR, HOTAIR, H19, UCA1 and ARSR." (PMID 39199690, 2024). "Apart from its legislative function, MALAT1 exhibits promise as a biomarker for many therapeutic uses, encompassing early cancer diagnosis, assessment of disease severity, and prognosis evaluation." (PMID 39323624, 2024). "Studies have demonstrated that MALAT1 promotes or suppresses cancer hallmarks, such as cell proliferation, metastasis, EMT, and chemoresistance." (PMID 39246994, 2024). "Forced MALAT1 expression in cancer cells and xenograft models led to increased cell growth, invasiveness, and movement, along with higher levels of MCP-1, CD68, CD163, CD206, and KI67." (PMID 38791954, 2024). "Introducing siRNA molecules into cancer cells reduced the levels of MALAT1, and MALAT1 inhibition significantly modulated chemokine (C-C motif) ligand 5-induced migration and invasion of CRC cells." (PMID 39471147, 2024). "Gallic acid regulated the expression of MALAT1, which was implicated with the EMT and tumorigenesis of HCC, and also extinguished the migratory status of cancer cells by downregulating the MALAT1/Wnt/β-catenin axis." (PMID 40176927, 2024). "The importance of MALAT1 transferred from M2 TAMs to tumor cells in cancer progression deserves further investigation in other cancers." (PMID 38639382, 2024). "Therapeutically, ASOs and siRNA targeting oncogenes like HER2, KRAS, and VEGF, as well as lncRNAs such as HOTAIR and MALAT1, and circRNAs like circPVT1 and circ_0000523, can inhibit cancer-promoting pathways and reduce tumor growth and metastasis." (PMID 39857631, 2024).
cancer (continued). "That being so, MALAT1 should be highlighted in further research, as it emerges as a promising target for cancer therapies, including gene therapies." (PMID 38674413, 2024). "The protective effect of XIST expression in various cancers is already well recognized, as well the oncogenic effect of MALAT1." (PMID 39148900, 2024). "Hypoxia in BC cells has been shown to trigger chromatin interactions unique to cancer cells, which raises MALAT1 transcription." (PMID 39323624, 2024). "Previous studies have demonstrated that the intercellular transfer of MALAT1 through exosomes enhances proliferation, invasion, and metastasis in various cancers." (PMID 39401197, 2024). "In a variety of cancer types, MALAT1 is shown to play a key role in promoting cell survival as well as growth." (PMID 39323624, 2024). "Generally, It is important to note that the role of MALAT1 in cellular processes can vary depending on the specific cellular context and cancer type." (PMID 39471147, 2024). "MALAT1 is known for its high expression levels in different cancers, and it was among the most abundant lncRNAs in the WT HCT116 cells, and its expression is further increased in TKS4 KO cells." (PMID 38672463, 2024). "Notable lncRNAs implicated in the advancement of cancer include HOX Transcript Antisense RNA (HOTAIR) and metastasis-associated lung adenocarcinoma transcript 1 (MALAT1)." (PMID 39483548, 2024). "It is interesting to identify MALAT1, a long non–coding RNA involved in cancer metastasis, as a target of both miR221 and miR483–3p overexpression." (PMID 38339342, 2024). "MALAT1 has been shown to act as a tumor suppressor or a tumor promoter, depending on the cancer type examined, or even to have opposite roles in the same cancer type." (PMID 38791553, 2024). "On the other hand, several studies provide evidence that cancer fusion proteins can affect tumorigenicity by enhancing MALAT1 expression." (PMID 38919532, 2024). "Controversial reports exist between in vitro and in vivo studies regarding Malat1’s function in nuclear speckles and cancers." (PMID 39714456, 2024). "On the other hand, it seems that MALAT1's effects on cuproptosis varied depending on the cancer cell line." (PMID 39325172, 2024). "Metastasis-associated lung adenocarcinoma transcript 1 (MALAT1), a universally expressed lncRNA with strong evolutionary conservation, was discovered to be greatly overexpressed in a number of human cancers." (PMID 39170516, 2024). "LncRNA MALAT1 has been demonstrated to play a significant role in the occurrence and development of various cancers through the ceRNA regulation network." (PMID 39532842, 2024). "Albeit the role of MALAT-1 in cancer has been extensively studied, molecular mechanisms that regulate MALAT-1 are scarcely reported." (PMID 38201661, 2024). "Overall, small molecules, ASOs and Xeno-nucleic acids (XNAs) have therapeutic value in decreasing MALAT1 and MENβ levels in various cancer types." (PMID 38338910, 2024). "MALAT1, a member of the long non-coding RNA family, plays diverse roles in biological processes, including gene regulation, cellular proliferation, and cancer development." (PMID 39532842, 2024). "For instance, metastasis-associated lung adenocarcinoma transcript 1 (MALAT1) and nuclear-enriched abundant transcript 1 (NEAT1) are strongly implicated in cancer progression and metastasis in various cancer types." (PMID 39199690, 2024). "MALAT1, known for its oncogenic properties, has emerged as a critical player in several cancers, including CRC, where it enhances cell proliferation, angiogenesis, migration, and invasion while suppressing apoptosis." (PMID 39401197, 2024). "MALAT1 can influence cancer development by activating Wnt/-catenin, ERK/MAPK, and PI3K/AKT signaling pathways." (PMID 39471147, 2024). "The small MALAT1 molecule has a triple-helix structure, which is highly stable in cancer cells and less stable in other cell cultures." (PMID 38674413, 2024).
cancer (continued). "This review will dissect the mechanisms by which MALAT-1 modulates EMT to enhance cancer proliferation, metastasis, stemness, and chemoresistance." (PMID 38201661, 2024). "Understanding its precise molecular mechanisms is crucial for developing targeted therapies, and therapeutic strategies targeting MALAT-1 show promise for improving cancer treatment outcomes." (PMID 38511067, 2024). "MALAT-1 has been identified as a crucial regulator in cancer pathophysiology among the multiple molecular actors participating in these mechanisms." (PMID 38511067, 2024). "It's important to note that the specific mechanistic roles of MALAT-1 can vary among different cancer types and even within subtypes of a particular cancer." (PMID 38511067, 2024). "MALAT-1 also plays a significant role in cancer immunology by regulating diverse immune cell populations." (PMID 38511067, 2024). "According to the research in this review, MALAT-1 is a crucial regulator of cancer development and treatment effectiveness." (PMID 38511067, 2024). "As MALAT-1 has a variety of impacts on cancer cell proliferation, migration, invasion, and metastasis, it plays a multidimensional role in carcinogenesis." (PMID 38511067, 2024). "Then, we experimentally evaluated the effect of the NR4A1/MALAT1 axis on specific cancer types through MALAT1 downregulation and CRISPR-i assays." (PMID 38791553, 2024). "In summary, MALAT-1 is a versatile cancer regulator, influencing tumorigenesis, chemoresistance, and immunotherapy responses." (PMID 38511067, 2024). "Ever since the overabundance of MALAT1 and MENβ was correlated with various cancers, these lncRNAs have been targeted by small molecules as well as multiple nucleic acid-based agents." (PMID 38338910, 2024). "In vivo studies showed that these systems reduced MALAT1 expression in approximately 60% of tumor tissue, which was correlated with the inhibition of cancer cell proliferation." (PMID 39272802, 2024). "It was demonstrated that these nanoparticles were successfully transported into the nucleus, which resulted in the inhibition of MALAT1 expression in the A549 cancer cell line." (PMID 39272802, 2024). "In the course of CRC, MALAT1 stimulates the proliferation, invasion, and migration of cancer cells through PRKA kinase anchor protein 9 (AKAP-9), which is associated with cancer progression and metastasis." (PMID 38674413, 2024). "Small molecules like niclosamide, tyrphostin 9, imidazole-derived compound 5 and quercetin result in a 2-fold decrease in MALAT1 levels upon treatment with various cancer cell types." (PMID 38338910, 2024). "MALAT1 is one of the most studied non-coding RNAs in cancer, generally overexpressed in tumor progression and metastasis." (PMID 38611028, 2024). "This upregulation induced epithelial-mesenchymal transition (EMT) and a cancer stem cell phenotype, which was enhanced by MALAT1 sponging miR-124." (PMID 39256366, 2024). "MALAT1 lncRNA was thoroughly investigated in the context of cancer prognosis/entities and metastasis, so examples of the upstream regulation of MALAT1 transcription are tightly associated with cancer-related processes." (PMID 38674413, 2024). "The lncRNA MALAT1 (metastasis-associated lung adenocarcinoma transcript 1) has been shown to regulate invasion, migration, EMT and metastasis in a variety of cancers, including TNBC, in which it correlates with poor prognosis." (PMID 39272915, 2024). "Transforming growth factor beta (TGF-β)-induced upregulation of MALAT1 enhances cancer metastasis, which is mediated by an interaction with suz12 at the transcriptional level to alter downstream events." (PMID 39199304, 2024). "MALAT1’s role in cancer biology is performed via the regulation of important signaling pathways that are involved in rudimentary processes like cell division or maintaining cell identity." (PMID 38674413, 2024). "In cancer cells, MALAT1 has been shown to modulate H3K27 methylation and controls downstream genes expression." (PMID 39681821, 2024).